COL3A1 (collagen type III alpha 1 chain)
Diseases named in the same sentence as COL3A1 in open-access papers (continued):
Sharing a sentence is not in itself a finding about the gene and the disease.
heart failure (17 papers, 2019 to 2025). Inability of the heart to pump blood at an adequate rate to meet tissue metabolic requirements. "In our present study, the higher dose of P234 increased the expression of inflammatory (Tnf), fibrotic (Ctgf, Tgfb, and Col3a1), heart failure (Nppa), and cardiac remodeling-associated (Mmp9) genes compared to the CKD-only group, supporting our echocardiographic and histology results." (PMID 37640761, 2023). "Deletion of RalGAPα1 also exacerbated TAC-induced cardiac remodeling with upregulation of cardiac fibrosis and increased expression of heart failure markers such as Anp, Bnp, Col1a1 and Col3a1 in the RalGAPα1-cKO hearts as compared to the control hearts." (PMID 35879328, 2022). "Based on the inflammatory and fibrotic markers commonly observed in response to myocardial infarction and development of heart failure, we assessed the expression of mRNA for Tnfa, Il1b,Il6, Il18, Ccl2, Ccl3, Cxcl1, Cxcl2, Col1a1, Col3a1, Postn, and Tlr4 at 1 and 3 months." (PMID 35411847, 2022). "In addition, HC treatment significantly decreased Nppa, Nppb, Col1a1, and Col3a1 levels, known as major heart failure markers." (PMID 34679760, 2021). "Inclusively, the expression patterns of the most proteins (MMP-2, Col1a1, Col3a1, N-Cadherin, β-Catenin, CnA, RyR, SERCA2 and PTGS2) in human heart failure are consistent with the discoveries above in the Cre recombinase-induced cardiotoxicity model." (PMID 36834504, 2023). "The molecular indicators of heart failure (ANP and BNP) and fibrosis (Col1a1 and Col3a1) were elevated in the RV of PAB rats compared to sham rats." (PMID 37932744, 2023). "Concomitantly with cardiac dysfunction and heart failure, Tg-SCD hearts displayed the significant up-regulation of two major cardiac collagens, which are of type 1 and type 3, i.e., Col1a2 and Col3a1." (PMID 34576047, 2021). "While adenoviral overexpression of TCS22 failed to significantly regulate many heart failure-relevant transcripts (including brain natriuretic peptide, Anp, Il6 and Col1a), it did elicit a robust increase in Col3a1 in the LV." (PMID 36388115, 2022). "In addition, up-regulation of extracellular matrix proteins, Col1a2 and Col3a1, could reflect adverse fibrotic remodeling of Tg-SCD mice with symptoms of heart failure." (PMID 34576047, 2021).
Marfan syndrome (14 papers, 2013 to 2025). A disorder of the connective tissue. "Following investigations, a de novo probably-pathogenic variant was identified in the COL3A1 gene, which directed initial suspicion from Marfan syndrome to a final diagnosis of VEDS." (PMID 41466732, 2025). "Historically, genetic testing focused on core syndromic genes, such as FBN1, TGFBR1/2, and COL3A1, which collectively account for the majority of diagnoses in classic connective tissue disorders like Marfan syndrome, LDS, and vEDS." (PMID 40981152, 2025). "Canonical syndromic genes, such as FBN1 and COL3A1, are highly penetrant and account for the majority of Marfan syndrome and vascular Ehlers–Danlos cases, respectively." (PMID 40981152, 2025). "Causative genes include autosomal polycystic kidney disease (PKD1, PKD2), Ehlers–Danlos syndrome (COL3A1), Marfan syndrome (FBN1), Loeys–Dietz syndrome (TGFB2, TGFB3, TGFBR1, TGFBR2, SMAD2, SMAD3), and Majewski Osteodysplastic Primordial Dwarfism (PCNT)." (PMID 40004483, 2025). "Altogether, only 17 genes were primarily identified in relation to cervical insufficiency, with six being syndromic, i.e. COL1A1 and COL3A1 causing EDS; FBN1 causing Marfan syndrome; ZMPSTE24 and LMNA causing restrictive dermopathy; and MATR3 causing myopathy." (PMID 32214361, 2020). "Marfan syndrome (MFS) is associated with FBN1 mutations; Ehlers–Danlos syndrome (EDS) is relevant to the COL3A1 mutation; Loeysؘ–Dietz syndrome (LDS) is related to TGFBR1 or TGFBR2 mutations as well as SMAD3 or TGFB2 mutations." (PMID 36291545, 2022). "Moreover, as supported by the literature, several have been associated with hernia formation, Ehlers–Danlos syndrome, and Marfan’s syndrome (e.g., COL1A1, COL3A1, COL5A1, FBN1, and TIMP1)." (PMID 22648066, 2013).
colorectal cancer (13 papers, 2012 to 2025). A primary or metastatic malignant neoplasm that affects the colon or rectum. "Such as, in colorectal cancer, elevated COL3A1 expression has been associated with tumor growth, progression, and metastasis, indicating its potential as a prognostic marker." (PMID 38913913, 2024). "The expression of COL3A1 is significantly upregulated in breast, gastric, head and neck, and colorectal cancers, underscoring its potential as a prognostic predictor for these types of cancer." (PMID 39761856, 2025). "COL3A1 has been reported to be overexpressed in various cancers, including breast and colorectal cancers, where it contributes to ECM remodeling and enhances tumor invasiveness." (PMID 41465316, 2025). "Second: Long-term study of changes in the expression of GUCA2A and COL3A1 genes in a larger number of patients with colorectal cancer." (PMID 37816854, 2023). "First: Examining the expression of GUCA2A and COL3A1 in blood samples, serum, colorectal cancer cell lines, their role with using overexpression and knock-down methods of genes." (PMID 37816854, 2023). "Collagen type III (COL3A1) has been reported to promote cell proliferation, metastasis and invasion and is increased in colorectal cancer patients." (PMID 35642021, 2022). "A previous study demonstrated that the mRNA and protein levels of COL3A1 are not only present in colorectal cancer (CRC) cells, but also increased in the plasma of CRC patients, which is associated with clinicopathologic factors and poor survival." (PMID 34229299, 2021). "Previously, a variation in COL3A1 protein staining has been reported in e.g. epithelial tumor cells, in the cytoplasm but also in the nucleus of colorectal carcinoma, using 13,548–1-AP antibody from Proteintech." (PMID 31533654, 2019). "The upregulation of COL3A1 transcription was shown in colorectal cancers comparing with the normal counterparts by microarray gene expression analyses and RNA-seq technique." (PMID 26741506, 2016). "Furthermore, COL3A1 was increased in all six subtype of colorectal cancers." (PMID 26741506, 2016). "In colorectal cancer (CRC), the upregulation of COL3A1 predicted poor overall and disease-free survival." (PMID 37907993, 2023). "The PPI networks indicate the RAB31, COL1A1, COL1A2, COL3A1, COL11A1, and VCAN as the most important protein network that likely to be connected and show betweenness among themselves to significantly promote the prognosis of colorectal cancer." (PMID 33597969, 2021). "This seems counterintuitive, but in a previous study it has been shown that epithelial but not stromal expression of Col3A1 is a prognostic indicator of colorectal carcinoma." (PMID 34771536, 2021). "The result of the remained patients showed that, except for ITGB5, the other three genes COL1A1, FN1and SPP1were up-regulated in six cancer samples, and the COL3A1 was up-regulated in four cancer samples, suggesting the ECM-pathway genes are usually up-regulated in colorectal cancer." (PMID 22905095, 2012).
Obesity (13 papers, 2015 to 2025). Accumulation of substantial excess body fat. "HFD-induced obesity led to upregulated expression of extracellular matrix (ECM) genes (Col3a1, Col6a3, Eln, and Sparc) and downregulated expression of immunoregulatory genes (Iigp1 and Cxcl10) in these stromal subtype cells." (PMID 32785175, 2020). "This DS‐induced up‐regulation was aggravated in the presence of obesity, and significant synergy was observed for COL3A1 and FN1." (PMID 31368189, 2019). "Furthermore, it would be useful to investigate and compare the expression of Col3a1 in the fat depots of genetic and diet-induced animal models of obesity to further investigate the relationship between ColIII and adipogenesis." (PMID 33504048, 2021). "THBS1 is required for this shift, since the expression of numerous obesity-induced, ECM-related FAP genes (such as Fbn1, Col3a1, and Adamts5) is markedly blunted in HFD-fed KO mice." (PMID 38954467, 2024). "Consistent with findings from the early-stages of diet-induced obesity studies, our network analysis identified increased expression of common collagen-related ECM transcripts COL1A1, COL3A1, COL16A1, COL4A4, and COL6A3." (PMID 26678390, 2015). "Studying obesity with and without OSA, changes (unadjusted for multiple comparisons) in some peptides belonging to CDH13, FGB, COL1A1, and COL3A1 were also identified." (PMID 39858454, 2025).
renal fibrosis (13 papers, 2019 to 2025). A final common manifestation of a wide variety of chronic kidney diseases characterized by glomerulosclerosis and tubulointerstitial fibrosis. "Last, the lesser inflammation was associated with lower renal fibrosis and expression of profibrotic genes (Col1a1, Col3a1, Fn1, and Vim) in UUO kidney of Casp9 HZ mice." (PMID 34739325, 2021). "Confirming our dose range experiments, X203 reduced AKI-induced loss of kidney mass, limited renal fibrosis, and improved renal function while lowering inflammatory (Tnfα, Il6, Ccl2, Ccl5, Il1β), fibrosis (Col1a1, Col1a2, Col3a1, Fn1, Acta2) and tubular damage (Kim1, Ngal) markers." (PMID 36470928, 2022). "As expected, all strains showed an expression of collagen III (Col3a1) as evidence for the development of renal fibrosis in the chronic phase of kidney injury." (PMID 38791453, 2024). "Results from Western blot also showed a reduction in the expression of renal fibrosis-related proteins (αSMA, Fn-1, Col3a1) and inflammatory factors (IL-1β, IL-6, TGF-β) in the kidney of acetate-treatment group." (PMID 36922584, 2023). "Q-PCR indicated a significant reduction in the expression of renal fibrosis-related genes (fn-1, αSMA, Col1a1, Col3a1, Ctgf, fsp1, KIM) and inflammatory cytokines (Tgfα, Tgfβ, Il-1b, Il-4, Il-6, CD44, CD68) in the kidney of the acetate-treatment group." (PMID 36922584, 2023). "Measurement of mRNA levels of Col3a1 and Fn1, assessment of renal fibrosis by Masson’s trichrome staining, and quantification of α-SMA-positive areas revealed a marked decrease of fibrosis in kidneys treated with Bex." (PMID 36443310, 2022). "At the same time, expression of inflammatory cytokines (Il1b, Csf2, Tnfa, and Cxcl10), renal fibrosis, and profibrotic genes (Col1a1, Col3a1, Fn1, and Vim) was lower in the FA-treated Casp9 HZ mice." (PMID 34739325, 2021). "In contrast to the findings with Insig1ΔKap mice, fibroblast deficiency of Insig1 did not worsen UUO-induced renal fibrosis, as evidenced by unchanged collagen deposition and fibrotic indicator (Fn, Acta2, Col3a1, and Vim) mRNA expressions in the kidneys." (PMID 38806641, 2024). "The mRNA levels of α-SMA, Col1a1, Col3a1, and Postn were also reduced in the c-AblMyo−cKO mice, demonstrating that specific knockout of c-Abl in myofibroblasts effectively alleviated established renal fibrosis." (PMID 38689280, 2024). "However, the expression of ECM genes such as mesenchymal collagens Col3a1 and Col1a1 as well as EMT markers found in tumorigenic EMT or renal fibrosis, including EMT-associated cytoskeleton Vimentin, Fn1 and Sparc, were significantly increased in Smarca4cKO tubular cells." (PMID 37727504, 2023). "At day 7 post-UUO surgery, the extent of renal fibrosis was induced in Sirt2tKO kidneys; they displayed higher levels of CTGF, FN1, COL3A1, and α-SMA compared to WT mice after UUO surgery." (PMID 37777567, 2023). "Previous studies described that TGFβ1 enhanced α-SMA, COL1A1, COL3A1, and CTGF levels to drive renal fibrosis mediated by the miR-433." (PMID 30536131, 2019). "In order to validate that miRNA-184 promoted the progression of renal fibrosis by inhibiting HIF1AN expression, qRT-PCR assay was performed to determine the expression of α-SMA, GTGF, COL1A1, and COL3A1." (PMID 30536131, 2019). "The expression of renal fibrosis markers could potentially be affected by BMP signaling, but levels of Acta2 (α-smooth muscle actin), Col1a1 and Col3a1 (type I and III collagen α1 chains), Tgfb (TGF-β1), and Fn1 (fibronectin) were not significantly changed." (PMID 40773297, 2025).
bladder cancer (12 papers, 2017 to 2025). "Recently, COL3A1 was identified in association with the progression and prognosis of human bladder cancer." (PMID 37907993, 2023). "In bladder carcinoma, COL3A1 has been implicated in tumor invasion by regulating the MAPK signaling pathway, and in nasopharyngeal carcinoma, COL3A1 was identified as the only target of miR-29b in relation to migration and invasion." (PMID 33066614, 2020). "High COL3A1 levels were associated with a poor prognosis in bladder cancer." (PMID 31963366, 2020). "Interestingly, according to the correlations between COL3A1 expression and clinicopathological parameters in bladder cancer, we found that highly expressed COL3A1 could cause the progression of BCa and more local recurrence rate." (PMID 29050298, 2017). "As a result, we thought that COL3A1 played certain role in the progression of human bladder cancer and influenced the prognosis probably by regulating MAPK signaling pathway, which contributed to the poor prognosis of BCa." (PMID 29050298, 2017). "As an oncogene, COL3A1 was highly expressed in bladder cancer tissues, compared with normal bladder." (PMID 29050298, 2017). "COL3A1 has been identified as a representative biomarker that is overregulated in the focal adhesion pathway, and plays an unfavorable role in the development and metastasis of ovarian and bladder cancer." (PMID 34229299, 2021). "Meanwhile, GSEA analysis demonstrated that genes associated with focal adhesion and MAPK signaling pathway were enriched in bladder cancer samples with COL3A1 highly expressed, suggesting that COL3A1 might affect cell migration or invasion through MAPK signaling pathway." (PMID 29050298, 2017). "COL3A1 overexpression has been confirmed in multiple cancers, such as bladder cancer, while the impact of COL3A1 expression level in GC is not completely understood." (PMID 32509452, 2020).
keloid (12 papers, 2016 to 2025). An irregularly shaped, elevated mark on the skin caused by deposits of excessive amounts of collagen during wound healing. "We clustered collagen gene expression in keloids and lymphedema and found that keloid tissue tended to have higher expression of COL3A1, COL1A2, COL1A1, COL6A1, and COL5A1 than did the ML and SL groups." (PMID 40742741, 2025). "Among them, COL1A1 and COL1A2 encode type I collagen and COL3A1 encodes type III collagen, the major components of the extracellular matrix in keloid tissue." (PMID 35872873, 2022). "The diagnostic value of COL1A1, COL1A2, COL3A1, COL5A1, and COL5A2 between keloid and different control tissue was evaluated by different datasets." (PMID 35872873, 2022). "This decrease in CRIF1 abundance led to decrease in cell proliferation, migration, and mRNA expressions of COL1A1 and COL3A1, all of which play an integral role in keloid formation." (PMID 33436666, 2021). "The hub genes of COL1A, COL1A2, COL5A2, and COL3A1 indicate that genes related to collagen synthesis play a vital role in the pathogenesis of keloids." (PMID 35222522, 2021). "Lipo-PGE1 also decreased COL1A1, COL1A2, and COL3A1 mRNA expression and the total soluble collagen level in keloid fibroblasts." (PMID 28644845, 2017). "Moreover, when PTB was suppressed, there was a reduction in excessive deposition of FN1 and COL3A1 in transplanted keloid tissues." (PMID 27897224, 2016). "Moreover, COL3A1 was reduced in transplanted keloid tissues with PTB suppression, although its expression had not been changed after TGF-β1 treatment and PTB suppression in vitro." (PMID 27897224, 2016). "Moreover, in keloid tissue, a positive correlation was noted between the level of Foxp3 expression and the level of encoding type III collagen (type III collagen alpha 1, COL3A1) expression and the COL3A1/type I collagen alpha 1 (COL1A1) ratio." (PMID 37867188, 2023). "RSL3 injection into keloid tissue dramatically decreased the mRNA levels of fibrotic genes, such as α-SMA, COL1A1, COL1A2, COL3A1, and FN1, and downregulated the ECM contents, according to qPCR analysis and the Sircol test." (PMID 40860189, 2025). "In our study, the results of ENCORI prediction and RT-qPCR showed that miR-29a-3p can regulate the expression of COL1A1, COL1A2, COL3A1, COL5A1, and COL5A2, and these target genes were closely related to the development of keloid." (PMID 35872873, 2022). "Genes involved in extracellular matrix formation including COL1A1, COL3A1, POSTN, COL1A2, FN1, and ASPN were significantly upregulated in keloid compared to the normal skins." (PMID 35990663, 2022). "It was downregulated in keloid and can negatively regulate the expression of COL1A1, COL1A2, COL3A1, COL5A1, and COL5A2." (PMID 35872873, 2022). "Previous studies have confirmed that miR-29a-3p was significantly downregulated in keloid tissues and fibroblasts and can regulate the proliferation, apoptosis, migration, and invasion of KFs by targeting COL1A1 and COL3A1." (PMID 35872873, 2022). "Transcriptome analysis showed that the core differentially expressed genes related to collagen synthesis play a vital role in the pathogenesis of keloids, including COL1A, COL1A2, COL5A2, and COL3A1." (PMID 35222522, 2021). "When the diagnostic value of these key genes were evaluated between the normal skin from keloid-prone or normal individuals (GSE113619), the AUC values of COL1A1, COL1A2, COL3A1, COL5A1, and COL5A2 in keloid were 0.650, 0.625, 0.575, 0.525, and 0.450, respectively." (PMID 35872873, 2022). "Compared with normal skin, type I and III collagen deposition in keloid tissue increased significantly, and previous studies have confirmed that miR-29a-3p can regulate the biological behavior of KFs by directly targeting COL1A1 and COL3A1." (PMID 35872873, 2022).
keloid (continued). "The results may explain the lower cell density and ECM accumulation in the PTB siRNA group, and suggest that PTB regulates cell proliferation and transcription of COL3A1 and FN1 in vivo in keloid tissues." (PMID 27897224, 2016). "Additionally, inhibition of PTB led to a reduction in excessive deposition of collagen type III alpha 1 chain (COL3A1), demonstrating that PTB siRNA promoted regression of keloid tissue in vivo by regulating both dermal cell proliferation and extracellular matrix accumulation." (PMID 37875914, 2023). "In the PTB siRNA group, the expressions of COL3A1 and FN1 but not COL1A1 significantly decreased in keloid xenograft tissues." (PMID 27897224, 2016).